HIF1A (hypoxia inducible factor 1 subunit alpha)
Diseases named in the same sentence as HIF1A in open-access papers (continued):
Sharing a sentence is not in itself a finding about the gene and the disease.
diabetic nephropathy (continued). "In diabetic nephropathy, ferroptosis can trigger renal tubule damage through the HIF-1α pathway by upregulating HO-1 expression, leading to iron overload, excessive ROS production, and lipid peroxidation." (PMID 37990310, 2023). "Hypoxia and elevated HIF-1α are important contributors to peritoneal fibrosis during PD and Canagliflozin was reported to have an inhibitory effect on HIF-1α in diabetic nephropathy." (PMID 37251320, 2023). "have demonstrated that HIF-1α/HO-1-mediated ferroptosis plays a significant role in the pathogenesis of diabetic nephropathy." (PMID 37876811, 2023). "LncRNA 1700020I14Rik reduces cell proliferation and fibrosis via the miR-34a-5p/Sirt1/HIF-1α signaling pathway in diabetic nephropathy." (PMID 37988356, 2023). "One study suggested that HIF-1α exerts a protective role in diabetic nephropathy by upregulation heme oxygenase-1 (HO-1) expression to regulate the mitochondrial dynamics." (PMID 36211825, 2022). "Previous study has found that OIP5-AS1 regulates HIF-1α expression in diabetic nephropathy via miR-34a-5p/Sirt1 axis." (PMID 34513821, 2021). "Fortunately, berberine was reported to activate HIF-1A to adapt to the stressful conditions and protected tubular epithelial cells from apoptosis in diabetic nephropathy rats." (PMID 32025234, 2020). "In diabetic nephropathy (DN), hypoxia‐inducible factor‐1α (HIF‐1α) activation in tubular cells plays an important protective role against kidney injury." (PMID 32975326, 2020). "In another study investigating the effect of SO therapy in diabetic nephropathy rats, HIF-1-α gene expression levels was reported to be decreased in the ozone therapy group." (PMID 31800874, 2020). "This study provides a novel perspective on HIF‐1α in DN‐by not only developing a new research field in diabetic kidney disease but also laying a foundation for the identification of promising therapeutic targets." (PMID 32975326, 2020). "In conclusion, we found that luseogliflozin, an SGLT2 inhibitor, ameliorated diabetic nephropathy at least partly by inhibiting HIF-1α accumulation." (PMID 31611596, 2019). "Induction of HIF-1α function attenuates progression in animal models of diabetic foot ulcers, diabetic nephropathy, and diabetic cardiomyopathy." (PMID 31214621, 2019). "On the other hand, HIF-1α inducer cobalt chloride improves disease manifestations in a variety of kidney disease models including diabetic nephropathy and hypoxic preconditioning ameliorates LPS-induced renal dysfunction." (PMID 23984430, 2013). "Studies have shown that HIF-1α can exert protective effects against tubular injury in diabetic nephropathy via HO-1-mediated control of mitochondrial dynamics, suggesting complex interactions between HIF-1α signaling, oxidative stress responses, and mitochondrial function." (PMID 41508092, 2026). "Similarly, proximal tubule-specific knockout of HIF-1α aggravates tubular injury and mitochondrial dysfunction in diabetic nephropathy models." (PMID 41602837, 2026). "Furthermore, HIF-1α also participates in the occurrence and development of diabetic kidney disease through mechanisms such as regulating apoptosis, inducing mitochondrial autophagy, and vascular calcification." (PMID 39995420, 2025). "The role of HIF-1α varies in disease models of non-diabetic nephropathy." (PMID 40040789, 2025). "Drawing from insights gained through the network pharmacology and molecular docking analysis, a compelling hypothesis emerges: SKP’s mitigation of ferroptosis in diabetic nephropathy primarily hinges on the inhibition of HIF-1α/HO-1 signaling pathway." (PMID 38403669, 2024).
diabetic nephropathy (continued). "Furthermore, in diabetic nephropathy models, silencing SIRT1 protein promotes fibrosis and inflammation factor expression by upregulating HIF-1α protein, accelerating diabetic nephropathy progression, whereas overexpressing SIRT1 has the opposite effect." (PMID 39408861, 2024). "Diabetic kidney disease is characterized by increased activation of HIF-1α, combined with HIF-2α suppression that may importantly contribute to glomerular and renal tubular dysfunction, in apparition and progression of renal disease." (PMID 36142323, 2022). "Collectively, our study indicates that miR-122-5p could ameliorate tubular injury in diabetic nephropathy via FIH-1/HIF-1α pathway." (PMID 35166173, 2022). "The activation of HIF1α has been demonstrated to improve diabetic nephropathy." (PMID 36297381, 2022). "In another study of diabetic kidney disease, sodium-glucose cotransporter 2 inhibition could suppress HIF-1α-mediated metabolic switch from lipid oxidation to glycolysis and exert a kidney protective effect." (PMID 34660710, 2021). "In this study, we investigated whether ferroptosis aggravated diabetic nephropathy (DN) and damaged renal tubules through hypoxia-inducible factor (HIF)-1α/heme oxygenase (HO)-1 pathway in db/db mice." (PMID 33679620, 2021). "Hirudin has been reported to be useful to preventing diabetic nephropathy (DN) and diabetic peripheral neuropathy, and the potential molecular mechanisms mainly include the inhibition of HIF-1α/VEGF and p38 MAPK/NF-κB pathways, or the activation of NRF-2/HO-1 pathways." (PMID 33935784, 2021). "Western blotting, flow cytometry, qRT-PCR, ELISA, PAS staining and immunohistochemical staining were used for assessment of TAB1/nuclear factor-κB (NF-κB)/hypoxia-inducible factor-1α (HIF-1α), iNOS, glycolysis, inflammation and the clinical and pathological manifestations of diabetic nephropathy." (PMID 33044562, 2020). "Studies have shown that HIF1α expression was detected in diabetic nephropathy renal tissues." (PMID 32754616, 2020). "Finally, a recent report has shown that HIF‐1α blockade prevented the development of diabetic nephropathy in type 1 diabetic mice." (PMID 30614190, 2019). "Interestingly, a genetic association study in diabetic patients and mice demonstrated that the HIF-1α Pro582Ser polymorphism exhibits a negative correlation with the risk of diabetic nephropathy, suggesting a protective function." (PMID 41357227, 2025). "Therefore, it indicated that miR-122-5p could ameliorate tubular injury in diabetic nephropathy via the FIH-1/HIF-1α pathway." (PMID 36364144, 2022). "However, the precise role of HIF-1α of diabetic nephropathy in the etiopathogenesis remains unclear." (PMID 36142323, 2022). "The Hif-1α upregulation may be involved in renal interstitial fibrosis in Diabetic Nephropathy." (PMID 35046888, 2021). "CA9 and PDK1, the downstream genes of HIF1A, and PDK4, the downstream gene of PPARA, were activated by both EZP and EYP, which showed the potential new targets of diabetic nephropathy." (PMID 40417738, 2025). "This study proposed a novel perspective for the treatment of diabetic nephropathy by analyzing the mechanisms of ZGP and YGP through the transcriptional regulatory networks of PPARA and HIF1A." (PMID 40417738, 2025). "HIF1A, PPARA, and SREBF1 were key transcriptional factors for the treatment of diabetic nephropathy by EZP and EYP in renal function." (PMID 40417738, 2025). "In the present study, we elucidated the novel anti‐diabetic nephropathy mechanism of ZGP and YGP through PPARA and HIF1A transcriptional regulatory networks and their specific downstream genes CA9, PDK1, and PDK4." (PMID 40417738, 2025). "In the renal context, Hif1α plays an important role in both acute and chronic kidney disease (CKD) such as ischemia-reperfusion injury (IRI) or diabetic kidney disease (DKD), respectively." (PMID 40739162, 2025).
diabetic nephropathy (continued). "In contrast, HIF‐1α inhibition and hypoxia‐mimicking HIF‐2α activation slow the progression of diabetic nephropathy." (PMID 37904700, 2023). "The expression levels of HIF-1α, KIM1, and COL-1mRNA and protein controlled by them in the kidneys of diabetic rats are significantly increased, suggesting that the diabetic nephropathy model is accompanied by changes in the HIF-1α/KIM1 pathway in kidneys." (PMID 36141135, 2022). "Thus, HIF1α signaling activated by lncRNA LINK-A may improve the treatment of diabetic nephropathy." (PMID 36297381, 2022). "The study clarified the mechanism of the ZGP and YGP by regulating the transcriptional regulatory network of HIF1A and PPARA and provided new ideas for the discovery of potential targets for the treatment of diabetic nephropathy and the development of natural nutrients." (PMID 40417738, 2025). "Although relatively few studies have investigated the relationship between iron death and HIF-1α in CRC, recent studies have found that HIF-1α plays an essential role in exacerbating diabetic nephropathy and tubular damage, indicating a promising direction for further investigation." (PMID 37881499, 2023). "Genes regulated by the hypoxia-inducible factor 1α (HIF-1α), including erythropoietin, are not increased in diabetic kidney disease (DKD)." (PMID 35409011, 2022). "Numerous studies showed that the HIF-1α/VEGF signaling pathway was involved in the regulation of the ECM, and the increased deposition of ECM was of great significance in the pathogenesis of diabetic kidney disease (DKD)." (PMID 33935784, 2021). "And transcription factors HIF1α, KLF4, KLF5, RUNX1, SP1, VDR, WT1 may be also related to diabetic nephropathy." (PMID 34735495, 2021). "Transcription factors HIF1α, KLF4, KLF5, RUNX1, SP1, VDR and WT1 may be related to diabetic nephropathy." (PMID 34735495, 2021). "Although an increment in HIF-1α expression improved nephrogenesis and hyperoxia-induced kidney injury, increased HIF expression was found in animal models of CKD and in renal biopsy material from patients with diabetic nephropathy and other forms of renal disease." (PMID 35955627, 2022).
nasopharyngeal carcinoma (68 papers, 2012 to 2025). A carcinoma arising from the nasopharyngeal epithelium. "There is limited evidence of an association between the survival of patients with EBV+ nasopharyngeal cancers and HIF-1α or VEGF expression." (PMID 33113858, 2020). "Also, the chemoresistance of nasopharyngeal carcinoma is associated with the upregulation of checkpoint inhibitor PD-L1, which is linked to enhanced aerobic glycolysis promoted by HIF1-α deregulation and LDH-A activity." (PMID 34025826, 2021). "HIF-1α depletion in nasopharyngeal carcinoma (NPC) cells leads to reduced MMP-13 in exosomes; in contrast, MMP-13 is overexpressed in exosomes under hypoxia, enhancing tumor cell migration and invasion." (PMID 40534881, 2025). "The lncRNA PVT1, for example, modulates nasopharyngeal carcinoma cell proliferation by stabilizing HIF-1α and activating KAT2A acetyltransferase." (PMID 37946265, 2023). "It has been shown that nasopharyngeal carcinoma-derived vesicles induced EMT phenotype in recipient cell through the direct transfer of HIF-1α and this modulation increase the migratory and pro-metastatic ability of these cells." (PMID 37838700, 2023). "In nasopharyngeal carcinoma, APα was demonstrated to regulate the growth and survival through modulation of the HIF-1α-mediated VEGF/PEDF signaling pathway." (PMID 36123698, 2022). "For instance, TFAP2A, an identified cofactor not found in any of the major databases, was demonstrated to interact with HIF1A to target the VEGF pathway in nasopharyngeal carcinoma cells." (PMID 36347941, 2022). "KAT2A recruited a nuclear receptor binding protein TIF1β by mediating H3K9 acetylation to activate NF90-maintained HIF1α stability, further enhancing nasopharyngeal carcinoma progression." (PMID 35449131, 2022). "Our previous study also revealed that HIF-1α played an important regulatory role in OL-enhanced radiosensitivity of nasopharyngeal carcinoma." (PMID 36050634, 2022). "For example, TFAP2A is overexpressed in human nasopharyngeal carcinoma and promotes tumorigenesis by influencing the HIF-1α/VEGF/PEDF pathway." (PMID 33713277, 2021). "Smoking or Nic exposure is reported to promote HIF1A expression in human nasopharyngeal carcinoma cells." (PMID 32894161, 2020). "HIF-1α activation is correlated with EBV-associated epithelial cancers, such as nasopharyngeal carcinoma and gastric cancer." (PMID 33363175, 2020). "As hypoxia-inducible factor-1α (HIF-1α) is overexpressed in nasopharyngeal carcinoma (NPC) tissues, we performed the present study to evaluate the efficacy profile of evofosfamide in NPC." (PMID 29764490, 2018). "EBV-positive nasopharyngeal carcinoma (NPC) cell-derived exosomes contain HIF-1α, which increases the migration and invasiveness of EBV-negative NPC cells." (PMID 30031392, 2018). "We found that Ang II was consistently present in HIF-1α-expressing regions of human nasopharyngeal carcinoma specimens." (PMID 28205588, 2017). "To further confirm this observation, we determined the expression levels of Ang II and HIF-1α in 13 human nasopharyngeal carcinoma specimens." (PMID 28205588, 2017). "EBV-positive nasopharyngeal carcinoma (NPC) cell-derived exosomes contain HIF-1α, which increases migration and invasiveness of EBV-negative NPC cells." (PMID 26156517, 2015). "In our study, we found that positive staining of HIF-1α was detected in 53.5 and 0 % of nasopharyngeal carcinoma cases and chronic nasopharyngitis tissues, respectively." (PMID 25377659, 2014). "Similarly, miR-455 in hiTDExs released from nasopharyngeal cancer cells were demonstrated to target ZO-1 in a HIF-1α dependent manner." (PMID 39928285, 2025). "The increased expression of miR-182-5p in nasopharyngeal carcinoma was partially induced by HIF-1α." (PMID 38062424, 2023). "In the initiation and progression of nasopharyngeal carcinoma, miR-338-3p inhibits migratory and proliferative abilities by targeting HIF1A directly, which could represent a novel therapeutic target." (PMID 35518349, 2022).
nasopharyngeal carcinoma (continued). "However, silibinin downregulated PD-L1 expression by modulating HIF-1α/LDH-A-mediated metabolism in nasopharyngeal carcinoma C666-1 cells and thus provided a potential avenue to overcome PD-L1-mediated resistance." (PMID 34025826, 2021). "Interestingly, in an RNA pull-down assay, CASC9 was demonstrated to directly bind to the HIF-1α protein in nasopharyngeal carcinoma, subsequently enhancing its stability." (PMID 32640630, 2020). "Finally, we show that the enhanced angiotensin II plays an important role in the intracellular accumulation of HIF-1α of hypoxic nasopharyngeal carcinoma cells and mediates the radiation-resistant phenotype of these nasopharyngeal carcinoma cells." (PMID 28205588, 2017). "Targeted by HIF-1α in nasopharyngeal cancer, acting in the initiation and progression of the tumor." (PMID 27551267, 2016). "Ex vivo experiments in nasopharyngeal carcinoma showed that the ILF2/ILF3 complex interacts with differentiation antagonizing non-protein coding RNA (DANCR) to stabilize the hypoxia-inducible factor 1 subunit alpha (HIF1A) mRNA, enhancing cell migration and invasion." (PMID 39735599, 2024). "In nasopharyngeal carcinoma (NPC), HIF-1α upregulates the expression of stearoyl-CoA desaturase 1 (SCD1), which mediates the production of monounsaturated fatty acids and inhibits ferroptosis." (PMID 35624785, 2022). "Compelling evidence has indicated the vital role of lysine-specific demethylase 4 A (KDM4A), hypoxia-inducible factor-1α (HIF1α) and the mechanistic target of rapamycin (mTOR) signaling pathway in nasopharyngeal carcinoma (NPC)." (PMID 34385569, 2021). "It was found that miR-338-3p inhibited cell migration and proliferation by HIF1A targeting in nasopharyngeal carcinoma (NPC) cells." (PMID 33827418, 2021). "Therefore, HIF-1α plays an important role in vasculogenic mimicry of nasopharyngeal carcinoma." (PMID 32993787, 2020). "HIF-1α, generally known as the core regulator of the hypoxic response, has been validated as a critical positive regulator of nasopharyngeal carcinoma (NPC) cell metastasis." (PMID 31799189, 2019). "Furthermore, HIF-1α overexpression was significantly associated with worse OS in oral carcinoma, nasopharyngeal carcinoma and oropharynx carcinoma, but not in laryngeal carcinoma (HR = 1.38; 95% CI: 0.87–2.19; I2 74%)." (PMID 24058651, 2013). "Additionally, HIF-1α overexpression was significantly associated with worse OS in oral carcinoma, nasopharyngeal carcinoma and oropharynx carcinoma, but not in laryngeal carcinoma." (PMID 24058651, 2013). "For instance, the oncogenic lncRNA PVT-1 is upregulated in nasopharyngeal carcinoma (NPC), which plays an important role in the radiation resistance of NPC by activating the KAT2A acetyltransferase and stabilizing HIF-1α." (PMID 39937018, 2025). "For example, in EBV‐infected nasopharyngeal carcinoma (NPC) cells, exosomes contain hypoxia‐inducible factor 1a (HIF1a) and latent membrane protein 1 (LMP1), which are involved in tumor development and progression in NPC." (PMID 39558933, 2024). "LCN2 was found to be highly expressed in the radioresistant nasopharyngeal carcinoma (NPC) cell line CNE2R, and there was a significant correlation between LCN2 expression and HIF-1α." (PMID 38778409, 2024). "Previous reports indicate that EBV-miR-BART1 relies on glycolysis to influence HIF1α through PTEN, leading to the metastasis and dissemination of nasopharyngeal carcinoma cells." (PMID 38686046, 2024). "Nasopharyngeal carcinoma-derived EVs can possess epithelial to mesenchymal transition (EMT)-inducing signals, including TGF-β, Hypoxia-Inducible Factor 1 alpha (HIF1α) and Matrix Metalloproteinases (MMPs)." (PMID 37829171, 2023). "The lncRNA PVT1 expressed in nasopharyngeal carcinoma cells was shown to promote their radioresistance by activating KAT2A acetyltransferase and stabilizing HIF1α." (PMID 33806538, 2021).